ATM (ATM serine/threonine kinase)
Diseases named in the same sentence as ATM in open-access papers (continued):
Sharing a sentence is not in itself a finding about the gene and the disease.
hereditary ovarian cancer (3 papers, 2017 to 2020). "Two-hit inactivation has also been described, in smaller case series, for PALB2- and ATM-related HBC, and BRIP1-related hereditary ovarian cancer." (PMID 32295625, 2020).
ischemic stroke (3 papers, 2022 to 2024). A stroke disorder caused by obstruction of blood flow to the brain, due to thrombotic (local blood clot formation) or embolic (due to a blood clot or other material traveling from another site) event. "AZD1390, an ataxia telangiectasia mutated (ATM) specific inhibitor, has been shown to promote radio‐sensitization and survival in central nervous system malignancies, while the role of AZD1390 in ischemic stroke remains unknown." (PMID 38668740, 2024). "Interestingly, in acute MI and ischemic stroke, the expression of APAF1 and IRAK3 was negatively correlated with the abundance of NK cells, while the expression of ATM, CAPN1, IL1B, IL1R1, PRKACA, PRKACB and TNFRSF1A was positively correlated with the abundance of NK cells in MI." (PMID 38526027, 2024).
latent infection (3 papers, 2016 to 2021). "Immunohistochemistry was also conducted to test whether EBV latent infection in the xenograft was maintained even though ATM gene was knocked out in the MKN1–EBV xenograft." (PMID 34503060, 2021). "ATM, ATR, and DNA-PKcs as well as several downstream targets are modulated by KSHV during both latent infection and lytic replication, thus creating a favorable environment for virus persistence and viral replication." (PMID 27258263, 2016).
leiomyosarcoma (3 papers, 2017 to 2025). An uncommon, aggressive malignant smooth muscle neoplasm, usually occurring in post-menopausal women. "In leiomyosarcoma, miR-181b overexpression using mimic decreased ATM expression." (PMID 41065894, 2025).
liver disease (3 papers, 2019 to 2026). "This ATM signaling pathway has been shown to play a role in other liver disease expressing high levels of oxidative stress such as metabolic dysfunction‐associated steatotic liver disease, hepatitis, and cholangitis." (PMID 41366830, 2025). "Much more, our data suggest that liver disease and metabolic alterations are inherent in the ATM gene." (PMID 31788461, 2019).
lung squamous cell carcinomas (3 papers, 2015 to 2024). "Missense point mutations of ATM in 9/212 lung squamous cell carcinomas (4 %) are present in the TCGA database." (PMID 26438152, 2015). "Missense point mutations in an extended analysis of ATM, MRE11A, RAD50 and NBN are present in 16/212 lung squamous cell carcinomas (7 %) are present in the TCGA database." (PMID 26438152, 2015). "However, the Lung-MAP SWOG S1400G trial (NCT02154490) found that talazoparib (Talzenna) had a lower ORR of 4% in patients with advanced refractory lung squamous cell carcinoma, specifically in tumors with BRCA1/2, ATM, ATR, and PALB2 mutations." (PMID 38989152, 2024). "To extend these findings we interrogated the publically available database of 212 lung squamous cell carcinomas in the TCGA to determine the incidence of alterations that are predicted to compromise ATM and ATR kinase activation and the FA pathway of ICL repair." (PMID 26438152, 2015).
myeloid leukemia (3 papers, 2014 to 2025). A clonal proliferation of myeloid cells and their precursors in the bone marrow, peripheral blood, and spleen. "Myeloid leukemia has been extremely rare in both ATM deficient mice and AT patients." (PMID 24474198, 2014). "ATM and CHEK2 variants create a higher risk of generating chromosomal translocations and other mutations associated with myeloid leukemia development." (PMID 40766138, 2025). "Mutations in ATM, MGA, KMT2A, MLLT10, NSD1, and TET2 have been commonly identified in several hematological neoplasms, including both acute lymphoid and myeloid leukemia." (PMID 38672648, 2024).
neuroendocrine carcinoma (3 papers, 2012 to 2021). A malignant neuroendocrine neoplasm composed of cells containing secretory granules that stain positive for NSE and chromogranin. "This is consistent with the clinical experience of the radiosensitivity displayed by high grade neuroendocrine cancers, driven by low expression of key DNA damage response enzymes, such as ATM and ATR36–38." (PMID 31953491, 2020).
Nijmegen breakage syndrome-like disorder (3 papers, 2015 to 2021). "The viability of this strategy is supported by the findings that subjects with A-T-like disorder and Nijmegen breakage syndrome-like disorder have impaired repair via reduced ATM activity but do not appear to have higher risks of malignancy." (PMID 33498525, 2021).
pancreatic NETs (3 papers, 2019 to 2024).
pancreatitis (3 papers, 2017 to 2023). Inflammation of the pancreas. "They include DNA damage response and DNA repair genes (ATM, BRCA1, BRCA2, and POLQ), pancreatitis gene (SPINK1) and cell apoptosis gene (CASP8)." (PMID 37234870, 2023).
premature ovarian failure (3 papers, 2020 to 2025). "ATM is involved in ovarian function, and ATM deficiency can induce premature ovarian failure." (PMID 32962729, 2020). "Repair of such lesions depends on the Ataxia-telangiectasia mutated (ATM)–BRCA1 DNA repair-associated (BRCA1)/2 pathway, and impaired DNA repair accelerates follicular attrition, potentially precipitating premature ovarian insufficiency (POI, also termed premature ovarian failure)." (PMID 40867818, 2025).
pulmonary arterial hypertension (3 papers, 2020 to 2025). Pulmonary arterial hypertension (PAH) is a group of diseases characterized by mean pulmonary artery pressure >20 mmHg and elevated pulmonary arterial resistance leading to right heart failure. "ATM encodes a serine/threonine kinase that plays a crucial role in DNA repair pathways, and as a sensor of oxidative stress, for which dysregulation has been reported to be connected to increased inflammation in pulmonary arterial hypertension." (PMID 39972178, 2025).
rhabdomyosarcoma (3 papers, 2012 to 2017). A rare aggressive malignant mesenchymal neoplasm arising from skeletal muscle. "However, this does not exclude a role for mTOR-dependent regulation of Chk2 in the DNA damage response as a recent report shows that in response to DNA damage, mTORC1 through FANCD2 is required for ATM-Chk2 activation in rhabdomyosarcoma cells." (PMID 25460505, 2015).
sarcopenia (3 papers, 2024 to 2025). Progressive decline in muscle mass due to aging which results in decreased functional capacity of muscles. "Using the MTA‐MO method, we identified 639 gene targets, and by analysing PPIs and querying public databases, we narrowed this list down to seven potential hub genes associated with sarcopenia (ESR1, ATM, CDC42, EP300, PIK3CA, EGF and PTK2B)." (PMID 40045692, 2025). "Applying MTA-MO to multi-omics data identified seven potential hub genes associated with sarcopenia: ESR1, ATM, CDC42, EP300, PIK3CA, EGF, and PTK2B." (PMID 41303670, 2025). "We subsequently investigated EEF1E1, a modulator of the ATM response to DNA damage that is involved in the regulation of cellular senescence and has not been previously linked to sarcopenia." (PMID 39276001, 2024).
schizophrenia (3 papers, 2008 to 2025). A major psychotic disorder characterized by abnormalities in the perception or expression of reality. "More association studies on larger samples from other populations are necessary to reveal the relevance of ATM polymorphisms as potential risk factors for schizophrenia and provide a deeper understanding of the genetic causes of the disease." (PMID 34650388, 2021). "Six SNPs in the ADSS gene and three SNPs in the ATM gene in a Chinese population of 488 schizophrenics and 516 controls were genotyped to examine their association with schizophrenia (SZ)." (PMID 19115993, 2008). "A recent study suggested the ATM gene as a possible candidate for schizophrenia susceptibility." (PMID 40259965, 2025). "Our present data suggest that the ATM gene is a candidate locus for susceptibility to schizophrenia and the variant G allele of the rs609429 polymorphism may provide valuable insight into its association with schizophrenia." (PMID 34650388, 2021). "Thus, ATM is potentially a candidate gene involved in the development of schizophrenia." (PMID 34650388, 2021).
synucleinopathy (3 papers, 2018 to 2025). A neurodegenerative disease that is characterized by the abnormal accumulation of aggregates of alpha-synuclein protein in neurons, nerve fibers or glial cells. "Here we used two different rodent models to show that synucleinopathy causes upregulation of three different markers of DNA damage in vivo—γH2AX, 53BP1, and p-ATM—specifically in dopaminergic neurons." (PMID 30050065, 2018). "In summary, our study demonstrates that ATM is aberrantly activated in a mouse model of α-synucleinopathy, and its pharmacological inhibition attenuates the DNA damage response, reduces neuroinflammation, and improves behavioral performance." (PMID 40723779, 2025). "In this study, we evaluated the therapeutic potential of AZD1390, a highly selective and brain-penetrant ATM inhibitor, in reducing neuroinflammation and improving behavioral outcomes in a mouse model of α-synucleinopathy." (PMID 40723779, 2025). "Overall, these results suggest that targeting the DDR via ATM inhibition reduces genotoxic stress, suppresses neuroinflammation, and improves behavioral outcomes in a mouse model of α-synucleinopathy." (PMID 40723779, 2025). "Expanding our investigation into an α-synucleinopathy mouse model, we assessed the impact of ATM inhibition on genotoxic stress, a key driver of neurodegeneration in PD." (PMID 40723779, 2025). "Notably, AZD1390 treatment reduced the expression of these cytokines, suggesting that ATM inhibition suppresses neuroinflammation in α-synucleinopathy." (PMID 40723779, 2025). "Our study demonstrates that AZD1390, a potent ATM inhibitor, exerts beneficial effects by reducing genotoxic stress (DNA damage), suppressing senescence and neuroinflammation, and improving behavioral function in a mouse model of α-synucleinopathy." (PMID 40723779, 2025). "Similarly, ATM is found to be specifically activated in the dopaminergic neurons to induce apoptosis in synucleinopathy models of PD." (PMID 37737187, 2023).
T-cell leukemia (3 papers, 2016 to 2018). A malignant disease of the T-lymphocytes in the bone marrow, thymus, and/or blood. "Interestingly, as shown here, in proliferating T-cell leukemia Jurkat cells, ATM inhibition exerted also a radio-sensitizing effect, which is in stark contrast to non-transformed T cells." (PMID 30323167, 2018). "Consequently, we modeled the specific impact of TCL1A after introduction into the ATM-biallelic mature T-cell leukemia lines HH (inducible) and Hut78 (stable)." (PMID 29449575, 2018).
thymic carcinoma (3 papers, 2017 to 2023). Thymic carcinoma (TC) is a type of thymic epithelial neoplasm characterized by a high malignant potential. "PARP inhibitors might also be effective in TETs harboring ATM mutations, which are, however, extremely rare and only demonstrated in one case of thymic carcinoma." (PMID 36836670, 2023). "The receptor tyrosine kinases ALK and ERBB4, the serine/threonine kinase ATM, and the GTPase NRAS were mutated in one thymic carcinoma each." (PMID 27844328, 2017). "A heterozygous deletion of ATM was noted in two (8 %) of 26 thymic carcinomas." (PMID 27844328, 2017).
tuberous sclerosis (3 papers, 2014 to 2023). Hereditary disease characterized by seizures, intellectual disability, developmental delay, and skin and ocular lesions. "It was recently shown that the overexpression of PEX3 induces ubiquitination-dependent NBR1-mediated pexophagy and that PEX19 associates with the tuberous sclerosis complex, which is part of the signaling cascade downstream of ATM activating pexophagy in the presence of ROS." (PMID 28817674, 2017). "Level of Hif1α is significantly elevated by hypoxia, which undergoes phosphorylation by ATM to increase REDD1 that activates the tuberous sclerosis complex and results in inhibition of mTORC1 activity." (PMID 25333702, 2014).
uveal melanoma (3 papers, 2018 to 2024). A melanoma derived from melanocytes of the uveal tract. "GZ17-6.02 killed uveal melanoma cells through multiple convergent signals including enhanced ATM-AMPK-mTORC1 activity, inactivation of YAP/TAZ and inactivation of eIF2α." (PMID 38758815, 2024). "We previously observed intron retention in POLD1 (exon 22–23), PNKP (exon 19–20), ATM, and ATR in uveal melanoma cell lines treated with PRT543 with concomitant loss in protein expression." (PMID 37861290, 2023). "Germline or somatic mutations in ATM have not been described in uveal melanoma so far." (PMID 29769598, 2018). "In all three of our cases, ATM mutations cooccurred with pathogenic somatic variants in the BAP1 gene and two tumors have partial loss of chromosome 3, which are also relatively common event in metastasizing uveal melanoma, both associated with worse prognosis." (PMID 29769598, 2018).
ZIKV infection (3 papers, 2020 to 2022). "The CDK5 signaling pathway was predicted to be inhibited in the presence of the activation of ATM after ZIKV infection." (PMID 32708879, 2020). "Hammack and colleagues reported that ZIKV infection activates the ATM/Chk2 signaling pathway in human neural progenitor cells and inhibits progression of cells through S phase, leading to an increase in viral replication." (PMID 32708879, 2020). "Defective ATR/Chk1 checkpoint has been reported previously in ZIKV infection in human NPC, while the ATM/Chk2 checkpoint was reported active, but only at 48 hpi." (PMID 35412344, 2022).
actinic keratosis (2 papers, 2011 to 2023). A precancerous lesion of the skin composed of atypical keratinocytes.
acute kidney injury (2 papers, 2018 to 2020). Sudden and sustained deterioration of the kidney function characterized by decreased glomerular filtration rate, increased serum creatinine or oliguria. "Acute kidney injury must be carefully monitored when ATM inhibitors become available in clinical practice in the future." (PMID 32157166, 2020).
acute pancreatitis (2 papers, 2022). An acute inflammatory process that leads to necrosis of the pancreatic parenchyma. "RNA‐seq data discovered that compared to untreated mice, IL‐23a, IL‐17a, and IL‐17f were remarkably increased while cell cycle‐related molecules, including ATM, Cdk2, and Chk2, were decreased in the mice with acute pancreatitis." (PMID 35634959, 2022). "Our study first discovered that the expression of IL‐23 was significantly increased by RNA‐seq in mice with severe acute pancreatitis, with a remarkable decrease in the expressions of cell cycle‐related molecules, including ATM, Cdk2, and Chk2." (PMID 35634959, 2022). "qPCR data also confirmed the upregulated levels of IL‐23a, IL‐17a, and IL‐17f and the downregulated levels of ATM, Cdk2, and Chk2 in the pancreatic tissues of mice with acute pancreatitis." (PMID 35634959, 2022).
Adenovirus infection (2 papers, 2020 to 2023). "Adenovirus infection blocks the ATM/ATR-mediated DDR through oncoprotein reorganization (E1b55K/E4orf6 and Edorf3) and degradation of the MRN complex." (PMID 32479542, 2020). "Interestingly, Adenovirus infection induces distinct virus and host-mediated ATM signals." (PMID 37376543, 2023).
aneurysm (2 papers, 2020 to 2022). Bulging or ballooning in an area of an artery secondary to arterial wall weakening.
asthma (2 papers, 2020 to 2023). "Moreover, the enhanced expression of ATM in airway epithelial cells of asthmatic children provides additional evidence of DNA damage establishment within the lungs, highlighting its pivotal role as a stress-induced mechanism operating across diverse cell types in the context of asthma." (PMID 37860000, 2023).
ataxia with oculomotor apraxia type 1 (2 papers, 2013 to 2022). "Other relatively common recessive ataxias include ataxia telangiectasia (A-T), ataxia with oculomotor apraxia type 1 (AOA1) and ataxia with oculomotor apraxia type 2 (AOA2), caused by mutations in the ATM-, APTX- and SETX-genes respectively, all of which encode proteins involved in DNA-repair." (PMID 35061740, 2022).
B-cell acute lymphoblastic leukemia (2 papers, 2024 to 2025). A neoplasm of lymphoblasts committed to the B-cell lineage, typically composed of small to medium-sized blast cells. "Recently, Chen et al54 uncovered a carcinogenic role for phosphorylated TET1 in B-cell acute lymphoblastic leukemia, driven by protein kinase C epsilon (PRKCE) and ataxia-telangiectasia mutated (ATM) kinases." (PMID 40520993, 2025).
basal cell carcinoma (2 papers, 2022 to 2023). A carcinoma involving the basal cells. "One such example is an ATM p.V242G variant that was passed down from a mother in one family with basal cell carcinoma to her daughter with anorectal melanoma." (PMID 37377903, 2023).
bone marrow failure (2 papers, 2020 to 2021). "Oxidative stress induced in HSCs of ataxia telangiectasia-mutated (ATM) knockout mice leads to a defect in the HSC function, resulting in a progressive bone marrow failure." (PMID 34422833, 2021).
bone tumors (2 papers, 2020 to 2025).
bowel cancer (2 papers, 2021 to 2024). "In this case-control study, mutations in 8 genes (APC, ATM, MLH1, FANCD2, MSH3, MSH6, PMS1, and RAD51D) were found to be associated with bowel cancer and were present in 3.5% of patients with bowel cancer." (PMID 35154239, 2021). "Mutations in APC, ATM, and MLH1 were associated with the highest risks of bowel cancer." (PMID 35154239, 2021).
brain glioma (2 papers, 2017 to 2024). A malignant glioma that involves the brain.
carcinoids (2 papers, 2017 to 2025).
cervical tumors (2 papers, 2012 to 2020). "The phosphorylation of ATM and the relocation of the protein into the nucleus have been suggested to act as predictive biomarkers of radiotherapy response and prognosis in specific tumors, such as cervical tumors." (PMID 32481544, 2020).